CCR2 (C-C motif chemokine receptor 2)
Diseases named in the same sentence as CCR2 in open-access papers (continued):
Sharing a sentence is not in itself a finding about the gene and the disease.
liver fibrosis (91 papers, 2010 to 2026). "In the context of the liver, CCR2 is implicated in several hepatic pathogenic processes, including acute liver injury, chronic hepatitis, liver fibrosis/cirrhosis and tumour progression." (PMID 39816386, 2024). "In summary, CVC attenuates liver fibrosis by inhibiting CCR2 and CCR2-associated proinflammatory and profibrotic signaling pathways." (PMID 37215993, 2023). "Meanwhile, CCL2/CCR2 axis has also been implicated in the regulation of macrophage recruitment and polarization in the disease models of liver fibrosis and renal fibrosis." (PMID 37667317, 2023). "In the same study, BDL- and CCl4-induced liver fibrosis, as assessed by collagen deposition, αSMA expression, and hydroxyproline content of the liver, was markedly reduced in CCR2-deficient mice." (PMID 34938271, 2021). "Impaired monocyte subset recruitment in CCR2-deficient mice reduces HSCs activation and diminishes liver fibrosis." (PMID 24058371, 2013). "CCR2+ monocytes might play a profibrotic role in schistosome-associated liver fibrosis and also be a target for treatment of schistosomiasis." (PMID 37817226, 2023). "In addition, pharmacological inhibition of CCR2 has been shown to reduce liver fibrosis in NASH, whereas CCR2 deficiency reduces macrophage aggregation and increases fibrosis." (PMID 36362037, 2022). "It has been further suggested using CCR2 deficient mouse model, that CCR2 critically controls intrahepatic Ly-6Chigh monocytes recruitment during liver injury via CCR2-dependent BM egress and promote the progression of liver fibrosis." (PMID 31849997, 2019). "In order to functionally address if macrophage recruitment played a role in the PNAC model, we took advantage of mice genetically deficient in Ccr2, which have been used in other liver injury models to demonstrate a role for recruited macrophages in liver fibrosis and alcohol-induced liver injury." (PMID 29643332, 2018). "CCR2 can contribute to hepatic fibrosis by influencing the mobilization of circulating monocytes to damaged hepatic cells and hepatic stellate cells (HSCs) through the activation of HSC." (PMID 39816386, 2024). "The oxidative stress condition provokes the inflammation and recruitment of Cx3cr1+Ccr2+MyD88+ Mo-macs that drive liver fibrosis via CX3CR1/MyD88/NF-κB/S100A pathway." (PMID 38684673, 2024). "It has been reported that HSCs promote hepatic macrophage infiltration through the CCL2/CCR2 pathway and induce M2 polarization to aggravate liver fibrosis." (PMID 38545255, 2024). "KCs can also release pro-inflammatory cytokines, including TNF-α and IL-1β, and recruit peripheral mononuclear macrophages to the liver through the CCL2/CCR2 axis, further aggravating liver fibrosis." (PMID 39635524, 2024). "Thirdly, the authors proposed targeting Cx3cr1+Ccr2+MyD88+ Mo-macs-mediated liver fibrosis, which showed improvement upon treatment with the MyD88 inhibitor, ST2825, in Mettl14-KO mice." (PMID 38684673, 2024). "Overall, these data indicate that Notch-induced MCP-1 secretion contributes to NASH-induced liver fibrosis, which can be blocked by CCR2 antagonists." (PMID 36752206, 2023). "For example, the m6A level of CCR2 (a chemokine receptor) is markedly elevated in the progression of liver fibrosis, while decreased in the reversal of liver fibrosis, indicating its potential as a therapeutic target." (PMID 37227534, 2023). "Researchers have revealed an association between C–C chemokine receptor type 2 (CCR2) and type 5 (CCR5) and their ligands (CCL2 and CCL5) concerning liver fibrosis." (PMID 37298632, 2023). "Increased liver MoMF infiltrate and liver fibrosis seen in opposite gain-of-function mice was ameliorated with concomitant hepatocyte Ccl2 knockout or CCR2 inhibitor treatment." (PMID 36752206, 2023). "Monocyte chemoattractant protein-1 (CCL2) can mediate C-C chemokine receptor-2 (CCR2)+ macrophage infiltration to promote liver fibrosis." (PMID 37908726, 2023).
liver fibrosis (continued). "Liver injury and liver fibrosis were induced by carbon tetrachloride (CCl4) in wild-type mice and Ccr2 knockout (Ccr2-/-) mice." (PMID 37215993, 2023). "CCR2, a promising target for treatment of liver fibrosis, was highly expressed in the advanced group and is essential for monocyte chemotaxis to the liver." (PMID 37817226, 2023). "CCR2 can promote liver fibrosis by regulating the migration of circulating monocytes to the injured liver and through activation of hepatic stellate cells (HSCs)." (PMID 35281057, 2022). "Based on these observations, cenicriviroc (CVC), a dual CCR2 and CCR5 antagonist, is expected to improve NASH and has been tested in clinical trials in patients with NASH-associated liver fibrosis." (PMID 35744024, 2022). "Chemokine-chemokine receptors play a key role in liver fibrosis, especially the C-C motif chemokine receptor 2 (CCR2) activates HSC." (PMID 35529927, 2022). "Cenicriviroc (CVC), a dual antagonist of these chemokines’ receptors, CCR2 and CCR5, has been tested in clinical trials in patients with NASH-associated liver fibrosis." (PMID 35744024, 2022). "Whereas an ALT decrease was observed following PEG-FGF21v treatment, liver fibrosis was mainly mitigated by CCR2/5 inhibition." (PMID 35743140, 2022). "It was determined that Ly6Chi monocytes promoted the development of liver fibrosis dependent on CCR2." (PMID 34853322, 2021). "In the present study, we found that aHSCs aggregate the macrophages through CCL2/CCR2 pathway and induce M2 phenotypic transformation during liver fibrosis." (PMID 33614685, 2021). "A previous study showed that infiltrated macrophages expressed CD68, CCR‐2, and Ly6c and that CCR‐2−/− mice had less inflammatory cell infiltration and hepatic fibrosis, suggesting that hepatic recruitment of macrophages promotes NASH through CCR‐2." (PMID 34390210, 2021). "In mouse models of hepatic fibrosis, either targeted deletion or pharmacological inhibition of CCR2 or CCR5 resulted in lower immune-cell activation and reduced liver fibrosis." (PMID 31377844, 2019). "In this review, we focus on the distinctive and complementary contributions of CCR5 and CCR2/CCL2 in HIV infection, multiple sclerosis, liver fibrosis and associated hepatocellular carcinoma." (PMID 31377844, 2019). "The important role of the CCL2-C-C motif chemokine receptor 2 [CCR2] signaling in liver fibrosis has been established in several experimental models using CCL2- or CCR2-deficient mice." (PMID 31805036, 2019). "Similar to its therapeutic effects in experimental studies, the C-C motif chemokine receptor 2/5 (CCR2/5) antagonist cenicriviroc (CVC) improved hepatic fibrosis and systemic inflammation in NASH patients." (PMID 30002817, 2018). "More importantly, transferring M(IL-13) that were transduced with either miR-130a-3p mimics or miR-142-5p ASO into the CCL4-treated Ccr2−/− mice rendered much milder liver fibrosis compared with transferring the untransduced M(IL-13) cells." (PMID 26436920, 2015). "Upon injury, CCL2/CCR2 signaling induce infiltration of Ly6C+ inflammatory monocytes into the liver resulting in the promotion of liver fibrosis as well as angiogenesis." (PMID 25852818, 2015). "CCR2/CCR6 deficient mice fail to recruit Ly6C+ monocytes and are thus protected from CCL4-induced hepatic fibrosis." (PMID 25852818, 2015). "The MCP-1/CCR2 axis in the liver was shown to play a critical role in the migration of inflammatory cells, leading to hepatic fibrosis and cirrhosis." (PMID 26484872, 2015). "In these studies, mice deficient in CCR2 have reduced hepatic macrophage infiltration associated with reduced HSC activation and diminished liver fibrosis." (PMID 24475094, 2014). "Collectively, these data indicate that inflammatory Ly6C+ monocytes, recruited into the injured liver via CCR2-dependent bone marrow egress, promote the progression of liver fibrosis." (PMID 23259611, 2012).
liver fibrosis (continued). "Experimental murine models identified an essential role for the CCR2-dependent infiltration of classical Gr1/Ly6C+ monocytes in hepatic fibrosis." (PMID 20548789, 2010). "In experimental murine models, the chemokine receptors CCR2, CCR1 or CCR5 that are differentially expressed on monocyte subsets have been implicated in hepatic fibrosis progression." (PMID 20548789, 2010). "CCR2 signaling exhibits dual regulatory properties at different stages of liver fibrosis." (PMID 42094612, 2026). "Our findings reveal that Tet2−/− pMDMs are a major source of elevated Ccl2 and Ccl8 in Tet2ΔMye-CCl4 mice, and Tet2−/− monocytes showed an increased expression of Ccr2 and Ccr3, which, thus, created a positive feedback loop that amplifies MDMs infiltration and liver fibrosis." (PMID 41474968, 2026). "Some have also proposed that the binding of MCP3 to its receptor CCR2 may promote the migration of hepatic stellate cells and Kupffer cells, potentially contributing to the progression of liver fibrosis." (PMID 39457577, 2024). "In NAFLD patients, serum levels of chemokines CCL2 was associated with inflammation and advanced hepatic fibrosis, FGF21 was associated with inflammation;In murine models of NASH, CCR2/5 inhibition reduced circulating Ly6C(hi) MoMFs, and the FGF21 agonist reduced body weight, hepatic triglycerides." (PMID 36875101, 2023). "C-C motif chemokine receptor 2 (CCR2) is an attractive target for treating liver fibrosis." (PMID 37215993, 2023). "However, significant advancements in treating liver fibrosis have been achieved by administering an oral antagonist targeting CCR2 and CCR5 known as cenicriviroc." (PMID 37298632, 2023). "Another study reported impaired resolution of liver fibrosis in CCR2 knockout mice." (PMID 37108548, 2023). "Inhibiting infiltrating Ly6Chi monocytes in CCR2-/- mice was shown to relieve liver fibrosis." (PMID 35707538, 2022). "Knockout of CCR2 or inhibition of CCL2 could alleviate liver fibrosis, indicating that Ly6Chi monocytes/macrophages are pro-fibrotic cells and play roles in aggravating tissue damage." (PMID 35990625, 2022). "PSMP could recruit inflammatory macrophages through CCR2 to infiltrate and promote M2-type polarization of macrophages and directly activate HSCs, ultimately promoting the progression of liver fibrosis." (PMID 35281057, 2022). "MoMFs, key effector cells in the hepatic immune activities, are derived from infiltrated bone marrow-derived CCR2+CX3CR1loLy6Chi monocytes, whose recruitment is dependent on the CCL2-CCR2 axis, which has been well-recognized in plenty of liver diseases including liver fibrosis and hepatic carcinoma." (PMID 36052075, 2022). "To explore whether CCL2/CCR2 axis has a crucial role in macrophage phenotypic changes during liver fibrosis, we treated the M0MΦ with recombinant human CCL2 or its specific receptor antagonist INCB-3284." (PMID 33614685, 2021). "Monocyte-derived CCR2 is an important commander in promoting liver fibrosis." (PMID 34853322, 2021). "Moreover, inflammatory Gr1+ monocytes were recruited into injured liver in a CCR2-dependent manner and differentiated into LY6Chi CD11b+ F4/80+ macrophages that strongly promoted liver fibrosis." (PMID 32708044, 2020). "Additionally, use of CCR1-, CCR2-, CCR5-, and CCR8-deficient mice or pharmacological inhibition of these axes reduced hepatic macrophage infiltration, hepatic fibrosis, and hepatocellular damage in experimental models of chronic liver injury." (PMID 31921154, 2019). "In order to abrogate this response, we treated aged TBI mice with cenicriviroc (CVC), a potent, oral, dual-antagonist of CCR2/5, which is currently being evaluated in a phase 2 clinical trial in adults with non-alcoholic fatty liver disease and liver fibrosis (NCT02217475)." (PMID 27090212, 2016). "In addition, the CCR2 ligand CCL2 is involved in liver fibrosis development by recruiting CCR2-expressing inflammatory macrophages." (PMID 24646914, 2014).
liver fibrosis (continued). "Furthermore, circulating miR-19b-3p has been reported to be involved in liver fibrosis via inhibition of C–C motif chemokine receptor (CCR2), indicating that up-regulation of circulating miR-19b-3p suppresses liver fibrogenesis via the regulation of inflammation." (PMID 35192632, 2022). "CCL2 could recruit CCR2+Ly-6Chi monocytes to develop into Ly-6C+ macrophages in the damaged liver; then, these Ly-6C+ macrophages provoked hepatic stellate cells (HSCs) and promoted hepatic fibrosis in mice." (PMID 33623529, 2021). "These experiments provide evidence for a vital role of MCP-1/CCR2-dependent Gr1hi monocytes infiltration in the development of liver fibrosis upon hepatic injury, thus suggesting that modulation of monocyte subset recruitment into liver may represent an approach for antifibrotic strategy." (PMID 24058371, 2013). "In the TANDEM trial (NCT03517540), LJN-452 with cenicriviroc, a dual CCR2/CCR5 antagonist, was used to study patients with biopsy-proven NASH and liver fibrosis." (PMID 40004240, 2025). "Deletion of CCR2 or CCR5 obviously suppressed inflammatory cell activation and restored liver fibrosis in preclinical liver fibrosis models." (PMID 40492139, 2025). "Cencriviroc, an antagonist of CCL2 and CCL5 receptors (CCR2/CCR5), is reportedly beneficial, with notably improved liver fibrosis in the treated patients." (PMID 40077628, 2025). "In the progress of liver fibrosis, peripheral pro-inflammatory mononuclear MoMφs can be attracted to the liver depending on CCL2/CCR2, CCL5/CCR5, and CCL1/CCR8 chemokines axis and aggravate liver fibrosis." (PMID 39635524, 2024). "Anti-CCR2/CCR5 drugs (NCT02217475; NCT03028740; NCT03059446; NCT02330549) for liver fibrosis and non-alcoholic steatohepatitis are in phase 2 or 3 clinical trials for antifibrotic therapy." (PMID 38476235, 2024). "Administration of cenicriviroc, a dual CCR2/CCR5 inhibitor, improved liver fibrosis in this PBC animal model." (PMID 37325634, 2023). "A dual C-C Motif Chemokine Receptor 2 (CCR2)/CCR5 antagonist, cenicriviroc (CVC), demonstrated improvement in NASH-related liver fibrosis and inhibition of steatohepatitis progression in a completed phase II clinical trial enrolling 289 patients with NASH." (PMID 36742318, 2023). "Pharmacological CCR2 inhibition with cenicriviroc (CVC) reduced ECM accumulation and liver fibrosis in prevention and treatment administration." (PMID 37215993, 2023). "The administration of a combination of a CCR2/ C-C chemokine receptor type 5 (CCR5) inhibitor and a fibroblast growth factor 21 analogue reduces the recruitment of these macrophages and liver fibrosis in a murine model of NASH." (PMID 36362037, 2022). "Cenicriviroc, a CCR2/CCR5 inhibitor, is being used in clinical trials for the treatment of liver fibrosis in nonalcoholic steatohepatitis patients." (PMID 35662287, 2022). "Cenicriviroc (CVC) is a C-C chemokine receptor type 2 (CCR2) and type 5 (CCR5) dual antagonist that inhibits liver fibrosis." (PMID 36263163, 2022). "During acute liver injury and chronic liver diseases such as liver fibrosis, CCR2+Ly6Chi monocytes are recruited to the liver in a manner dependent on the CCL2/CCR2 or CCL1/CCR8 chemokine-receptor interaction." (PMID 35707538, 2022). "In our study, the CCR2/5 inhibition, using a novel oral CCR2/5 antagonist (BMS-687681), strongly reduced the number of MoMF, and led to improved liver fibrosis." (PMID 35743140, 2022). "In line with this, cenicriviroc, an oral dual CCR2/CCR5 antagonist, has demonstrated anti-fibrotic effects in a thioacetamide-induced rat liver fibrosis model and in a mouse model of diet-induced NASH." (PMID 34938271, 2021). "Cenicriviroc is a dual antagonist of CCR2 and CCR5, It has been proven to alleviate liver fibrosis in mice, and its anti-fibrotic effect has been demonstrated in the clinical data of phase IIb." (PMID 34853322, 2021).
liver fibrosis (continued). "Since a study found some anti-fibrotic effects of CCL2 inhibitor in animal models of liver fibrosis, the pathway of CCL2/CCR2 as potential therapeutic targets should be further investigated by future studies." (PMID 33614685, 2021). "Cenicriviroc, an oral inhibitor of CCR2 and CCR5, significantly reduced the recruitment of hepatic Ly6C+ monocytes, inhibited alcohol-induced steatohepatitis and ameliorated liver fibrosis in mice." (PMID 32708044, 2020). "In a recent research, therapeutic inhibition of inflammatory monocytes recruitment by CCR2/CCR5 antagonist reduces steatohepatitis and liver fibrosis in mice." (PMID 31546702, 2019). "The role of CCR2 in promoting HSC chemotaxis and the development of hepatic fibrosis has been shown in animal models." (PMID 27246604, 2016). "Taken together, these observations render the CCL2/CCR2 and the CX3CR1 pathways important targets for developing potential therapies for the treatment of liver fibrosis." (PMID 25852818, 2015). "Impaired monocyte subset recruitment in CCR2-/- and CCR2-/-CCR6-/- mice resulted in reduced HSC activation and diminished liver fibrosis." (PMID 23259611, 2012). "Independent studies highlighted the importance of the chemokine receptor CCR2 and its cognate ligand monocyte-chemoattractant protein 1 (MCP-1/CCL2) for monocyte recruitment during experimental hepatic fibrosis." (PMID 20548789, 2010). "Several recent independent animal studies defined an important function of CCR2 and MCP-1/CCL2 for hepatic fibrosis." (PMID 20548789, 2010). "Endothelial p300 is a regulator of gene transcription with the properties of activating NF-κB pathway, promoting CCR2+ monocytes/macrophages accumulation and increasing CCL2 expression in the damaged liver, ultimately resulting in portal hypertension and liver fibrosis." (PMID 41333471, 2025). "In detail, Cx3cr1+Ccr2+ Mo-macs can be categorized into M1-like macrophages and S100A4-positive macrophages and then further activate hepatic stellate cells (HSCs) to promote liver fibrosis." (PMID 38627387, 2024). "However, during pathological conditions such as hepatic steatosis, liver inflammation, and liver fibrosis, a large number of peripheral monocyte-derived LAMs precursor cells are recruited to the liver by the CCL2/CCR2 axis and then differentiate into LAMs." (PMID 39635524, 2024). "Hence, the inhibition of CCL2/CCR2, CCL5/CCR5, and CCL1/CCR8 chemotaxis shows potential efficacy to repair liver fibrosis." (PMID 39635524, 2024). "Response to inflammatory signals Ly6Chi monocytes could rapidly infiltrate in inflamed tissues mostly dependent on chemokine receptors C-C motif chemokine receptor 2 (CCR2), CCR6 and CCR8 and results in enhanced liver fibrosis." (PMID 36865559, 2023). "However, limited investigations have been conducted to explore the mechanism by which CCR2 inhibition reduces ECM accumulation and liver fibrosis, which is the focus of this study." (PMID 37215993, 2023). "Inhibition of CCR2/CCR5 was accompanied by significantly reduced infiltration of hepatic macrophages, serum alanine transaminase (ALT) levels and liver fibrosis." (PMID 35743140, 2022). "Additionally, the C-C motif chemokine receptor 2 (CCR2+) monocytes, which are derived from bone marrow and recruited to the liver by CCR2, are crucial in contributing to hepatic fibrosis, since their inhibition has been reported to ameliorate NASH." (PMID 36032141, 2022). "CCR2 (a receptor for CCL2) and CCR5 (a receptor for CCL3 and CCL4) have been proposed to be targets for antifibrotic therapy due to their ability to promote liver fibrosis and macrophage infiltration." (PMID 35662287, 2022). "Among various CCR2 inhibitors, the effect of Cenicriviroc, a CCR2/CCR5 co-inhibitor, is verified in the phase II clinical trial of 289 patients with nonalcoholic steatohepatitis and liver fibrosis." (PMID 35990625, 2022).